RNU6-1290P (RNA, U6 small nuclear 1290, pseudogene)
Gene: Small nuclear RNA gene on chromosome 2 (175,029,769 to 175,029,877, forward strand). Ensembl gene ENSG00000199827.
Homologues: Orthologues: chimpanzee U6 (97% identical), macaque U6 (95% identical), mouse Gm24927 (82% identical), mouse Gm22509 (80% identical), guinea pig U6 (77% identical), pig U6 (76% identical). Paralogues in human: RNU6-12P (85% identical), RNU6-13P (85% identical), RNU6-15P (85% identical), RNU6-31P (85% identical), RNU6-32P (85% identical), RNU6-41P (85% identical), RNU6-1 (84% identical), RNU6-1011P (84% identical), RNU6-1024P (84% identical), RNU6-1145P (84% identical), RNU6-11P (84% identical), RNU6-166P (84% identical), and 1284 more.